INS (insulin)
Diseases named in the same sentence as INS in open-access papers (continued):
Sharing a sentence is not in itself a finding about the gene and the disease.
Obesity (continued). "To obtain information on the possible actors involved in the effects of vitamin E on insulin sensitivity, we measured the activation levels of JNK, one of the most studied factors in the obesity models of IR." (PMID 35883786, 2022). "The mechanisms underlying GDM are thought to be similar to other disorders of insulin sensitivity such as T2DM, prediabetes, obesity and PCOS." (PMID 36733795, 2022). "We herein demonstrated that aging and obesity increased the expression of active MT1-MMP which in turn cleaves IR to reduce its cell surface presentation and thereby suppresses insulin signaling." (PMID 35768470, 2022). "The previously widely accepted non-insulin-based IR indicators commonly included FPG, parameters of lipids, and indices of obesity, such as TyG, TyG-BMI, and TG/HDL-C." (PMID 36992743, 2022). "LETM1 impairs insulin signaling and the PI3K/PKB pathway in the adipose tissue of obese mice, and its expression is reduced in obesity." (PMID 35043013, 2022). "Results demonstrated SIT and MICT have equal benefits on aerobic capacity, insulin sensitivity, muscle capillarization and endothelial eNOS/NAD(P)H-oxidase protein ratio in men with obesity." (PMID 35564376, 2022). "A standardized multivariate regression model was constructed based on the glucagon predictors BMI-SDS, average liver fat, fasting insulin, glucose at 120 min, SPISE and ALT in overweight and patients with overweight/obesity." (PMID 36133310, 2022). "CGA has been shown to reduce oxidative damage, control the inflammatory response through inhibition of TNF-α, IL-6, and IL-1β, increase insulin sensitivity, and prevent CVD and obesity through lipid metabolism modulation." (PMID 35683374, 2022). "The role of insulin sensitivity/resistance is central to obesity-related NAFLD, the main comorbidity of obesity." (PMID 36142317, 2022). "Similarly, the association between BMI and endometrial cancer risk was attenuated when adjusted for BioT or fasting insulin, which influenced the risk of this cancer independent of obesity (BMI-adjusted BioT OR 1.91 [95% CI 1.47–2.48] and insulin OR 2.61 [95% CI 1.44–4.74])." (PMID 36558416, 2022). "Creatine has some anti-inflammatory and anti-oxidant characteristics, increases insulin sensitivity, and creatine metabolism and GATM has an important role in energy expenditure and defense against diet-induced obesity." (PMID 35625086, 2022). "Strong associations were identified of these phospholipids with triglycerides, but also with obesity related traits (e.g., waist, waist-hip ratio, total fat percentage, BMI and leptin), T2D and related traits (e.g. glucose, HOMA-IR and insulin)." (PMID 35022422, 2022). "The anti-obesity drugs also influenced serum biochemical parameters, such as TG, TC, GPT, insulin, OGTT levels, and fasting glucose." (PMID 36687627, 2022). "The overexpression of adiponectin increases AT expansion and improves insulin sensitivity in ob/ob mice and HFD-induced mouse models of obesity." (PMID 35909571, 2022). "In obesity cases, an imbalance between oxygen supply and tissue requirements might lead to increased infections in tissues, as a result of cellular infiltration, chronic low-grade systemic inflammation, and insulin resistance, further indicating the promotion of inflammation by HYX." (PMID 36213511, 2022). "The most important factors related to obesity, namely, HDL, LDL, total cholesterol, total glycerides, insulin, glucose, and gastric inhibitory peptides (GIP) levels, were analyzed in this study." (PMID 35204193, 2022). "Subjects with obesity have been reported to obtain higher IGF-I responses per dose level of hGH, possibly due to the interaction between GH and insulin on the hepatic GHR." (PMID 35521713, 2022). "We also assessed the direct impact of the MAIT cell secretome from adults with obesity (PWO) and IL-17 on insulin signalling." (PMID 35305128, 2022).
Obesity (continued). "Systemic hyperinsulinemia in pregnancy also occurs with endogenous factors such as obesity, GDM and T2D or exogenous factors (such as insulin use in type 1 diabetes or GDM)." (PMID 36733795, 2022). "In adolescents with obesity, the TyG index was superior to TG/HDL and inferior to fasting insulin with the hyperinsulinemic–euglycemic clamp." (PMID 36079745, 2022). "The FGF21 analogue LY2405319 was subcutaneously administered for 28 days to patients with obesity and T2DM, resulting in attenuated dyslipidaemia, reduced body weight and plasma insulin, and increased adiponectin levels." (PMID 36362103, 2022). "The objective of the study was to determine the effect of two doses of cholecalciferol (vitamin D3) supplementation on insulin action and BCF function in adolescents with obesity." (PMID 36364954, 2022). "BAT’s function is impaired during obesity, as cold-induced thermogenesis, insulin sensitivity, and glucose consumption are disrupted in the BAT of subjects affected by obesity." (PMID 36033972, 2022). "A reduction in levels of obesity seems to produce a reduction on TNF-α, which lead to a decline in leptin and an increase in adiponectin and insulin sensitivity." (PMID 35529460, 2022). "High-fat(HF)diet-induced obesity(DIO)mouse were established in our research, along with insulin resistance." (PMID 35534842, 2022). "In people with obesity, MAIT cell frequencies are reduced and biased towards a Th17 phenotype and can directly disrupt metabolic processes such as insulin-mediated glucose uptake." (PMID 35844529, 2022). "As a consequence, the reduction in adiponectin levels during obesity results in increased RANTES/CCL5 levels, which should induce an increase in insulin secretion." (PMID 35628332, 2022). "We have shown that in a cohort of adults with severe obesity who completed a 24-week milk-based LELD, there were substantial increases in adiponectin and reductions in leptin and LAR, consistent with increased insulin sensitivity." (PMID 35662920, 2022). "Analysis of differentially regulated phosphosites revealed phosphorylation dependent deregulation of insulin signaling as well as lipogenic and lipolytic pathways during HFD induced obesity." (PMID 35406736, 2022). "Possible biological pathways explaining the co-occurrence of obesity and depressed mood, as reported here, include inflammatory activation, disturbed hypothalamic–pituitary–adrenal (HPA) axis and altered insulin metabolism." (PMID 35194360, 2022). "This treatment resistance was attributed to insulin activating the PI3K/AKT pathway and this perhaps plays a role in treatment failure in patients with obesity." (PMID 36038791, 2022). "Moreover, numerous studies have demonstrated that oxidative stress and inflammation contribute to the progress of obesity by inducing skeletal muscle dysfunction and reducing energy expenditure, as well as by inducing the resistance of leptin and insulin which could govern energy homeostasis." (PMID 36466427, 2022). "Therefore, the present study hypothesized that saroglitazar could modulate adipose tissue dysfunction, obesity-related inflammation, improve insulin sensitivity in MSG obese Wistar rats, and may prove an innovative therapeutic strategy to ameliorate obesity and associated co-morbidities." (PMID 36033946, 2022). "They reported that adipogenic and insulin signaling genes (CEBPB, PPARG, ADIPOQ, IRS-1, IRS-2, GLUT4, among others) were downregulated in obesity." (PMID 36432612, 2022). "Ablation of NLR family pyrin domain containing 3 (NLRP3) inflammasomes in obesity reduced inflammation and adipose tissue IFN-γ and improved insulin sensitivity." (PMID 36552805, 2022). "Here, we mainly studied the effects of HTE on obesity in liver and adipose tissue and found that AKT, AMPK, and insulin signalling played roles in those tissues." (PMID 39280956, 2022).
Obesity (continued). "The intervention with OliveOil+DietBra effectively decreased the levels of fasting insulin, IL-1α and adiponectin, suggesting its beneficial role in improving the inflammatory profiles and fasting insulin levels in adults with class II/III obesity and T2DM." (PMID 35586621, 2022). "Reportedly, INS and LEP are closely related to obesity, while PTPN11 was identified in the studies of histiocytic sarcoma and Noonan syndrome." (PMID 35529938, 2022). "The anti-obesity property of COX-2 was restricted to males given the modest effects of COX-2 KO on body weight and insulin sensitivity in female mice." (PMID 35681514, 2022). "An important finding of this work is that, even though all treatments reduced the obesity-induced increase in the HOMA-IR, only obese mice supplemented with CSAT+® showed preserved insulin sensitivity in the liver and in skeletal muscle." (PMID 36139877, 2022). "We found that leptin (50.2% of the effect of BMI on pre-eclampsia), fasting insulin (27.7%–36.6%), and ISI (19.1%–50.1%) each mediated the total genetically predicted effects of obesity traits on female reproductive disorders." (PMID 35104295, 2022). "Pregnant women with overweight or obesity have higher FPG, insulin, and TG, compared to normal weight pregnant women." (PMID 35421281, 2022). "These inflammatory responses inducing IR in obesity and T2DM are not limited to impaired insulin signaling pathways; complex interactions of multiple metabolic pathways have also been implicated." (PMID 36177037, 2022). "Therefore, during aging, regulation and renewal of adipose tissue cells may be disrupted due to the altered insulin signaling and differentiation potential of senescent MSCs, promoting the development of serious metabolic diseases, including metabolic syndrome and obesity." (PMID 36467400, 2022). "In contrast, even in this small sample, fasting insulin and HOMA-IR were significantly higher in participants with obesity." (PMID 36570168, 2022). "Another commonality between obesity, T2DM, and metabolic syndrome is insulin resistance, the impaired response to insulin resulting in elevated levels of blood glucose." (PMID 35159155, 2022). "Decreased AdipoR1 and AdipoR2 expression in the liver of db/db mice, an animal model of human obesity, exhibited diminished adiponectin-induced AMPK and PPAR activation resulting in glucose intolerance as well as reduced insulin sensitivity." (PMID 35055468, 2022). "Partial leptin reduction improved leptin and insulin sensitivity and decreased body weight in mice with HFD-induced obesity." (PMID 36012616, 2022). "This genus has been suggested to counteract harmful obesity effects by stimulating the GLP-1 secretion, which can improve liver function and enhance glucose and insulin sensitivity as well as host energy metabolism." (PMID 35314754, 2022). "Resveratrol does appear to have some beneficial effects on insulin sensitivity, fasting plasma glucose, and blood pressure in people with T2D, and in the co-formulation of tRES-HESP in those overweight and with obesity." (PMID 35889827, 2022). "In consistent with the attenuated obesity phenotype, the HFD challenged Ido1-aKO mice exhibited significantly improved glucose tolerance and insulin sensitivity." (PMID 35715443, 2022). "The levels of insulin and IGF are influenced by various factors such as diabetes mellitus, acromegaly, excess energy, hypertriglyceridemia, dietary pattern, obesity, etc.." (PMID 36059323, 2022). "Since systemic inflammation is an important mediator of impaired insulin and IGF-1 signaling in obesity, we next assessed systemic inflammatory markers." (PMID 35628414, 2022). "The highest predicted probabilities of intermediate hyperglycemia and obesity occurred around the upper limits of CRP and insulin and the lower limits of adiponectin." (PMID 35757631, 2022).
Obesity (continued). "Mice with the IKKε gene removed that were fed a high-fat diet that induced obesity showed an upregulation of UPC1 in BAT and had normal insulin sensitivity." (PMID 36012526, 2022). "Both C3H and B6 are protected from obesity when CD44 is inactivated, but results varied by mouse strain for liver fat and insulin sensitivity." (PMID 35410390, 2022). "Increased acetate can affect host metabolism by causing increased pancreatic β-cell activity, glucose-stimulated insulin secretion (GSIS), hyperphagia, and obesity." (PMID 35754734, 2022). "Our findings confirm (A) a positive correlation of fasting GCGN with hepatic fat content and insulin sensitivity in subjects with T2DM, obesity, and fatty liver." (PMID 35662921, 2022). "In fact, GPR21 has been suggested to play a role in affecting body weight, insulin sensitivity, and glucose tolerance as GPR21 KO mice have improved insulin response and are protected from obesity." (PMID 35054972, 2022). "Some of the common features between the sexes of obesity-induced CRC include increased levels of leptin, IL-6, insulin, and C-reactive proteins (CRP-1), and decreased adiponectin levels." (PMID 36429114, 2022). "In this study, we investigated the effect of central insulin action on neural BOLD food-cue reactivity in men and women with normal weight, overweight and obesity." (PMID 35715625, 2022). "In obesity and T2DM, macrophages infiltrate metabolic organs such as the liver and adipose tissue, leading to low-grade inflammation that impairs insulin action." (PMID 36177037, 2022). "Accordingly, Ip6k1 deletion diminishes insulin secretion whereas transgenic mice that express a hyperactive IP6K1 display augmented insulin release, congenital hyperinsulinemia, and obesity." (PMID 35216174, 2022). "Therefore, independently of PCOS, MTF can re-establish levels of molecules involved in insulin/adiponectin signaling in endometrial cells, suggesting an improvement in insulin action and reproductive failures observed in endometria from women with obesity/PCOS." (PMID 35409282, 2022). "An elevated CTRP9 level in obesity is a compensatory response due to CTRP9 effect (glucose lowering and insulin sensitizing)." (PMID 35370782, 2022). "Bacterial DNAs were markedly enriched in pancreatic β cells of patients with obesity/T2DM, as evidenced by a robust 16s rRNA intensity within insulin+ cells." (PMID 35091566, 2022). "The leptin-deficient db/db mouse model used in our study has previously been shown to be affected by the metabolic disorders of obesity and T2DM, including elevated blood glucose and abnormal insulin secretion." (PMID 35915136, 2022). "Hirsutella sinensis may reduce diet-induced obesity and metabolic disorders by increasing levels of Parabacteroides goldsteinii in the gut, improving intestinal integrity, reducing metabolic endotoxemia, inflammation, insulin resistance, and inducing thermogenesis." (PMID 36532435, 2022). "Fasting insulin, HOMA-IR, and leptin levels were significantly elevated in hypothyroid children compared to the control group; more in hypothyroid children with obesity." (PMID 35501770, 2022). "The present research highlighted that the deletion of the liver's IDE worsened the resistance of insulin and glucose intolerance concerning HFD-induced obesity, accompanied by an expansion in plasma insulin levels." (PMID 36304965, 2022). "While the pregnant state is naturally associated with peripheral insulin resistance to maximize glucose availability for the developing fetus, pregnant women with obesity have 50-60% higher postprandial insulin levels and are more glucose intolerant than those without obesity." (PMID 36329895, 2022). "Early-pubertal girls with obesity also had significantly higher values (p < 0.05) for BMI-SDS, leptin, IGF-1, IGFBP3, insulin and HOMA-IR, LH, ratio LH/FSH, ACTH, DHE-S, androstenedione, testosterone and free testosterone levels than control group." (PMID 35412268, 2022).
Obesity (continued). "We calculated the proportion of total obesity effect mediated by leptin, fasting insulin, and ISI for disorders where the effects of obesity traits and mediators were significant at unadjusted P < 0.05." (PMID 35104295, 2022). "This prospective study was undertaken to determine the variations in insulin response to OST, adiponectin, and phenotypic markers of obesity in a cohort of Finnhorses throughout the year." (PMID 34713928, 2022). "P. distasonis can reduce obesity and related disorders in both ob/ob mice and HFD-fed mice by increasing insulin sensitivity." (PMID 35495722, 2022). "Genetic or diet-induced models of obesity would act via PERK to enhance obesity-induced insulin resistance, in which IRE1 was also shown to lower insulin responsiveness." (PMID 36743909, 2022). "Recently, interest has grown around the implication of GPx3 in obesity and IR, identifying GPx3 as a potentially novel regulator of IRS-1 expression and insulin sensitivity in WAT." (PMID 36079831, 2022). "Adipogenesis is correlated with various signaling pathways, such as insulin signaling and the PPAR regulation pathway, which are promising drug targets for obesity and metabolic disease treatment." (PMID 35096424, 2022). "Consumption of a high-fat diet or diet-induced obesity (DIO) increases body weight, insulin resistance and macrovesicular steatosis; however, these preclinical models do not produce significant hyperglycemia." (PMID 35409324, 2022). "A total of 524 blood samples from children with obesity (age 10–16 years old) were analyzed for FBG, lipids, insulin, leptin, and adiponectin." (PMID 35370951, 2022). "The present review explored the molecular and physiological adaptations of leptin, insulin, POMC, and AgRP neuropeptides to IF protocols, mostly performed in animal obesity models." (PMID 35445066, 2022). "Similarly, obesity in men leads to male infertility mediated through the altered hypothalamic-pituitary-gonadal axis, testicular steroidogenesis, metabolic dysregulation of insulin, cytokines, and adipokines, oxidative stress, and genetic and epigenetic changes." (PMID 36320802, 2022). "Olive oil combined with DietBra decreased fasting insulin, IL-1α and adiponectin, while inducing a reduction in BMI and weight in individuals with T2DM and class II/III obesity." (PMID 35586621, 2022). "Thereby, metabolically healthy obesity (MHO) was put forward to define such a phenotype of obesity without elevated blood pressure, abnormal lipid profiles or low insulin sensitivity." (PMID 36589938, 2022). "We show evidence that link GDF11 to adipogenic differentiation, glucose, and insulin homeostasis, which are pointing towards potential beneficial effects of GDF11‐based “anti‐obesity” therapy." (PMID 35920128, 2022). "The following section aims to assess the endocrine and metabolic factors, focusing on insulin, androgens and AMH (and their interactions) in women with PCOS, diabetes and obesity and how they impact the fetoplacental unit." (PMID 36733795, 2022). "In the reverse MR analysis, we also observed effects of BMI (both childhood and adult) on obesity-related biomarkers, such as CRP, IGF1, insulin, leptin, and TNFR2." (PMID 36253437, 2022). "For example, obesity reversibly suppresses GH secretion driven by elevated free fatty acids, whereas IGF-I levels remain normal or elevated due to elevated portal insulin levels." (PMID 35774144, 2022). "Both GLP-1 and GIP increase insulin secretion by pancreatic β-cells, but GIP has also been reported to be an ‘obesity hormone’." (PMID 35440936, 2022). "Adipsin is known to stimulate insulin secretion from β cells and improve glucose tolerance; it also modulates WAT homeostasis and is down-regulated during obesity." (PMID 36079831, 2022). "Independent from obesity, expression of GHR, IGF-1 and IGFBP-3 was related to AT dysfunction,and increased insulin levels." (PMID 36384443, 2022).